ZNF438 (zinc finger protein 438)
Description:
Isoform 1 acts as a transcriptional repressor.
Synonyms: bA330O11.1
Tractability: PROTAC: ubiquitination databases record sites on it.
Gene: Protein-coding gene on chromosome 10 (30,820,207 to 31,032,110, reverse strand). Ensembl gene ENSG00000183621.
Subcellular location: Nucleus
Subcellular location (Human Protein Atlas): Nucleoplasm; Cytosol
Gene Ontology:
Molecular function: protein binding; DNA-binding transcription factor activity, RNA polymerase II-specific; sequence-specific DNA binding
Biological process: regulation of transcription by RNA polymerase II
Cellular component: nucleoplasm; nucleus
Genetic constraint (gnomAD): Loss-of-function variants: 23 observed, 36.97 expected, observed/expected ratio (o/e) 0.62, 90% interval 0.45 to 0.88. The upper end of that interval is the gene's LOEUF score, 0.88, which puts it in group 3 of 6, group 1 being the genes least tolerant of losing a copy. Missense variants: 994 observed, 1,043.4 expected, observed/expected ratio (o/e) 0.95, 90% interval 0.9 to 1. Synonymous variants: 362 observed, 381.73 expected, observed/expected ratio (o/e) 0.95, 90% interval 0.87 to 1.03.
Homologues: Orthologues: chimpanzee ZNF438 (97% identical), macaque ZNF438 (94% identical), guinea pig ZNF438 (67% identical), rat Zfp438 (63% identical), mouse Zfp438 (62% identical), pig ZNF438 (57% identical), tropical clawed frog znf438 (35% identical), zebrafish znf438 (29% identical), Caenorhabditis elegans spr-3 (8% identical), Caenorhabditis elegans unc-98 (7% identical), Caenorhabditis elegans T22C8.3 (6% identical), Caenorhabditis elegans T22C8.4 (4% identical). Paralogues in human: ZBTB38 (14% identical), ZBTB4 (13% identical).
Diseases named in the same sentence as ZNF438 in open-access papers:
ZNF438 is named in the same sentence as 12 diseases in open-access papers, as found by Europe PMC text mining. Sharing a sentence is not in itself a finding about the gene and the disease. The quoted sentences say what the papers report.
coronary heart disease (1 paper, 2023). "Two sites were referenced in ≥ 6 publications: cg01656216 (near ZNF438) related to vascular disease and epigenetic age, and cg03636183 (near F2RL3) related to coronary heart disease, myocardial infarction, smoking and air pollution." (PMID 36991458, 2023).
osteosarcoma (1 paper, 2022). A usually aggressive malignant bone-forming mesenchymal neoplasm, predominantly affecting adolescents and young adults. "The Kaplan–Meier survival analysis suggested that lower expressions of ATMIN, ZNF438, and ZNF597 and the higher expression of ZNF692 were associated with worse overall survival in osteosarcoma." (PMID 35281811, 2022).
Stroke (1 paper, 2025). Sudden impairment of blood flow to a part of the brain due to occlusion or rupture of an artery to the brain. "We identified 179 significant SNPs and five common risk genes for RA and stroke (IRF5, RNASET2, ZNF438, UBE2LS, and SYNGR1)." (PMID 39953635, 2025).
ZNF438 also shares sentences with these, for which no sentence is quoted: ankylosing spondylitis (1 paper); Crohn disease (1); multiple sclerosis (1); myocardial infarction (1); psoriasis (1); seminoma (1); Sepsis (1); tumour (1); ulcerative colitis (1).